KLHL20 (kelch like family member 20)
Description:
Substrate-specific adapter of a BCR (BTB-CUL3-RBX1) E3 ubiquitin-protein ligase complex involved in interferon response and anterograde Golgi to endosome transport. The BCR(KLHL20) E3 ubiquitin ligase complex mediates the ubiquitination of DAPK1, leading to its degradation by the proteasome, thereby acting as a negative regulator of apoptosis. The BCR(KLHL20) E3 ubiquitin ligase complex also specifically mediates 'Lys-33'-linked ubiquitination. Involved in anterograde Golgi to endosome transport by mediating 'Lys-33'-linked ubiquitination of CORO7, promoting interaction between CORO7 and EPS15, thereby facilitating actin polymerization and post-Golgi trafficking. Also acts as a regulator of endothelial migration during angiogenesis by controlling the activation of Rho GTPases. The BCR(KLHL20) E3 ubiquitin ligase complex acts as a regulator of neurite outgrowth by mediating ubiquitination and degradation of PDZ-RhoGEF/ARHGEF11. In case of tumor, the BCR(KLHL20) E3 ubiquitin ligase complex is involved in tumor hypoxia: following hypoxia, the BCR(KLHL20)complex mediates ubiquitination and degradation of PML, potentiating HIF-1 signaling and cancer progression.
Synonyms: KLEIP; KLHLX; KHLHX; NEDSZFB
Tractability: Small molecule: it belongs to a druggable protein family. PROTAC: ubiquitination databases record sites on it; its protein half-life has been measured.
Gene: Protein-coding gene on chromosome 1 (173,714,919 to 173,786,820, forward strand). Ensembl gene ENSG00000076321.
Subcellular location: Cytoplasm, perinuclear region; Golgi apparatus, trans-Golgi network; Cell projection, axon; Cell projection, dendrite
Subcellular location (Human Protein Atlas): Cytosol; Golgi apparatus
Pathways (Reactome):
Immune System: Antigen processing: Ubiquitination & Proteasome degradation
Metabolism of proteins: Neddylation
Gene Ontology:
Molecular function: protein binding; type II interferon binding; ubiquitin-protein transferase activity; ubiquitin-like ligase-substrate adaptor activity
Biological process: Golgi to endosome transport; negative regulation of apoptotic process; proteasome-mediated ubiquitin-dependent protein catabolic process; protein K33-linked ubiquitination; protein ubiquitination; cytoskeleton organization; response to interferon-alpha
Cellular component: Cul3-RING ubiquitin ligase complex; cytoplasm; cytosol; Golgi apparatus; PML body; trans-Golgi network; actin cytoskeleton; axon; dendrite; perinuclear region of cytoplasm
Genetic constraint (gnomAD): Loss-of-function variants: 22 observed, 58.37 expected, observed/expected ratio (o/e) 0.38, 90% interval 0.27 to 0.54. The upper end of that interval is the gene's LOEUF score, 0.54, which puts it in group 2 of 6, group 1 being the genes least tolerant of losing a copy. Missense variants: 391 observed, 746.83 expected, observed/expected ratio (o/e) 0.52, 90% interval 0.48 to 0.57. Synonymous variants: 234 observed, 261.14 expected, observed/expected ratio (o/e) 0.9, 90% interval 0.81 to 1.
Gene-disease validity (ClinGen):
ClinGen rates the evidence that KLHL20 causes each of these diseases.
complex neurodevelopmental disorder (autosomal dominant): Moderate. A disorder that involves more than one phenotype associated with the central nervous system, including but not limited to intellectual disability, autism, and seizures (epilepsy).
Homologues: Orthologues: chimpanzee KLHL20 (100% identical), dog KLHL20 (100% identical), pig KLHL20 (100% identical), rat Klhl20 (100% identical), guinea pig KLHL20 (99% identical), macaque KLHL20 (99% identical), mouse Klhl20 (99% identical), tropical clawed frog klhl20 (98% identical), zebrafish klhl20 (96% identical), Drosophila melanogaster dbo (77% identical), Caenorhabditis elegans kel-20 (58% identical). Paralogues in human: KLHL17 (46% identical), KLHL2 (43% identical), KLHL1 (42% identical), KLHL5 (42% identical), KLHL3 (42% identical), KLHL8 (41% identical), KLHL12 (40% identical), KLHL4 (40% identical), KLHL28 (38% identical), KEAP1 (36% identical), KLHL18 (36% identical), IPP (34% identical), and 42 more.
Diseases named in the same sentence as KLHL20 in open-access papers:
KLHL20 is named in the same sentence as 18 diseases in open-access papers, as found by Europe PMC text mining. Sharing a sentence is not in itself a finding about the gene and the disease. The quoted sentences say what the papers report.
prostate carcinoma (7 papers, 2012 to 2019). A carcinoma that arises from epithelial cells of the prostate gland. "In human prostate cancer patients, higher levels of KLHL20 (and low PML) were found to correlate specifically with high-grade tumors." (PMID 31279627, 2019). "In line with this notion, KLHL20 expression is elevated in prostate cancers compared to its expression in benign prostatic hyperplasia." (PMID 27200299, 2016). "KLHL20 is induced by HIF-1α protein and forms a KLHL20-cullin 3 complex that degrades the promyelocytic leukemia protein (PML) leading to prostate cancer progression." (PMID 23676014, 2013). "Moreover, KLHL20 depletion in PC3 prostate cancer cells restricted the growth of tumor xenografts, suggesting KLHL20 as a potential therapeutic target." (PMID 31279627, 2019). "It would be intriguing to test whether MLN4924 attenuates prostate cancer progression induced by KLHL20-mediated PML degradation." (PMID 22935031, 2012). "Under hypoxic conditions, the hypoxia transcription factor HIF1α upregulates KLHL20, an E3 subunit, which promotes degradation of PML in a CDK2- and Pin1-dependent manner, thus promoting prostate cancer progression." (PMID 29416846, 2018). "In human prostate cancer, high expression of HIF-1α, KLHL20, and Pin1 is frequent observed and correlates with PML low expression." (PMID 27042198, 2016). "These clinical findings support the significance of KLHL20/PML pathway in the progression of prostate cancer and suggest a promise for targeting this pathway in the treatment of aggressive prostate cancers." (PMID 27042198, 2016). "Under hypoxic conditions, HIF-1 pathways upregulate the BTB protein KLHL20, and the Cullin3-KLHL20 E3-ligase targets the PML protein for degradation to potentiate HIF-1 signalling and disease progression in prostate cancer." (PMID 26544623, 2015). "Clinically, overexpression of HIF-1α, KLHL20, Pin1 and downregulation of PML are found in prostate cancers." (PMID 22935031, 2012).
Alzheimer disease (3 papers, 2019 to 2024). A progressive, neurodegenerative disease characterized by loss of function and death of nerve cells in several areas of the brain leading to loss of cognitive function such as memory and language. "Examples of known human genes associated with memory also identified in our study include: NTM and KLHl20 that are associated with Alzheimer’s disease and DOCK8 and KANK1 that are associated with neurodevelopmental disorders including memory potential." (PMID 32299497, 2020). "Further, it was observed that the fs-cb-miR-targeted gene KLHL20 was involved in Alzheimer’s disease while another gene, PAPD4, was found as a biomarker for diseases Hepatitis C virus infection." (PMID 38674383, 2024). "KLHL20 has emerged as an interesting target for drug development with potential application in both oncology and Alzheimer's disease." (PMID 31279627, 2019). "KLHL20 is a related CUL3-dependent ubiquitin ligase linked to autophagy, cancer, and Alzheimer's disease that promotes the ubiquitination and degradation of substrates including DAPK1, PML, and ULK1." (PMID 31279627, 2019). "The Cullin-RING E3 ligase KLHL20 has been shown to ubiquitinate some half a dozen protein targets that link its activities to diverse processes including autophagy, hypoxia, cancer, and Alzheimer's disease." (PMID 31279627, 2019). "KLHL20 is a BTB-Kelch family E3 ligase linked to autophagy, cancer, and Alzheimer's disease." (PMID 31279627, 2019). "The gene–disease-association in humans showed that targeted genes of fs-cb-miRs like KLHL20, BBIP1, and PAPD4 have acted as biomarkers for the diseases such as Alzheimer’s disease, Bardet-Biedl syndrome 18, and Hepatitis C virus infection, respectively." (PMID 38674383, 2024).
diabetes (3 papers, 2017 to 2023). "Impairment of KLHL20-mediated regulation of autophagy dynamics aggravates diabetes-associated muscle atrophy." (PMID 36646695, 2023). "Impairment of KLHL20-mediated regulation of autophagy dynamics potentiates starvation-induced cell death and aggravates diabetes-associated muscle atrophy." (PMID 36646695, 2023). "In particular, impairment of KLHL20-mediated autophagy regulation potentiates starvation-induced cell death and aggravates diabetes-associated myoatrophy." (PMID 34440082, 2021). "KLHL20-KO mice show that ablation of KLHL20 enhances diabetes-associated muscle atrophy." (PMID 29186924, 2017).
breast cancer (2 papers, 2021 to 2024). A primary or metastatic malignant neoplasm involving the breast. "However, targeted genes of fs-cb-miRs in humans like KLHL20, TNS1, and PAPD4 are associated with Alzheimer’s, malignant tumor of the breast, and hepatitis C virus infection disease, respectively." (PMID 38674383, 2024).
schizophrenia (2 papers, 2021 to 2023). A major psychotic disorder characterized by abnormalities in the perception or expression of reality. "In addition, human psychiatric diseases like schizophrenia or bipolar disorder can be caused by alterations in genes with high similarity to Pak (PAK1/2/3) and dbo (KLHL20 indirect, via regulation of Pak,)." (PMID 37759179, 2023).
B-cell lymphoma (1 paper, 2013). "It becomes apparent that PML is regulated by different molecules in different cancer types, e.g., by E6AP in B-cell lymphoma, CK2, and PIAS1 in NSCL cancer whereas KLHL20/Pin1 in prostate adenocarcinoma." (PMID 23730625, 2013).
cancer (12 papers, 2012 to 2025). A tumor composed of atypical neoplastic, often pleomorphic cells that invade other tissues. "Potential biomarkers of cancers with enhanced KLHL20 activity to degrade PML include increased HIF-1α and Pin1 levels." (PMID 40002221, 2025). "For example, CUL3, in complex with the substrate adaptor Ketch-like family member 20 (KLHL20), is thought to promote cancer progression through increased ubiquitination and degradation of the Promyelocytic leukemia (PML) protein." (PMID 29594129, 2018). "Since HIF-1α is frequently upregulated in tumors through hypoxia-dependent or -independent mechanism, KLHL20 expression is expected to be upregulated in certain cancers." (PMID 27200299, 2016). "In particular, we will focus on three Cul3 substrate adaptors, kelch-like ECH-associated protein (Keap1), kelch-like family member 20 (KLHL20), and speckle type BTB/POZ protein (SPOP), with the intent to highlight novel targets in cancer therapy." (PMID 27200299, 2016). "Four KLHL family members are associated with cancer: KLHL6, KEAP1 (KLHL19), KLHL20, and ENC1 (KLHL37)." (PMID 23676014, 2013). "KLHL20-based ubiquitin ligase is therefore a potential target of anti-cancer therapy." (PMID 27042198, 2016). "Thus, KLHL20 is capable of controlling the effectiveness of IFN-based anti-cancer therapy through destabilizing the pro-death factor DAPK." (PMID 27042198, 2016). "KLHL20 is an important KLHL family member related to cancer progression." (PMID 23676014, 2013). "Thus, the Roc1-Cullin3-KLHL20 complex represents the first PML ubiquitin ligase that is dysregulated in human cancers and the KLHL20-mediated PML destruction and HIF-1α feedback regulation contribute significantly to tumor progression." (PMID 22935031, 2012). "Thus, KLHL20 can restrict both apoptotic and autophagic cancer cell death." (PMID 31279627, 2019). "Further insights into the functional and mechanistic basis of KLHL20 and SPOP in cancer development can be obtained from studies with suitable animal models, especially genetically engineered mouse models." (PMID 27200299, 2016). "In particular, Keap1, KLHL20, and SPOP are the most reported Cul3 substrate adaptors for their impacts on various cancer types." (PMID 27200299, 2016). "Consistent with these tumor-promoting functions, aberrant expression of several key molecules of the KLHL20/PML pathway, such as HIF-1α, Pin1, and PML, has been reported in many types of cancers." (PMID 27042198, 2016). "Pertinently currently there are emerging several potentially druggable targets such as CK2, BMK1, KLHL20, and E6AP that has been demonstrated to negatively regulate PML stability in various pre-clinical cancer models." (PMID 23730625, 2013). "Quite a few E3s have been identified to mediate the proteasomal degradation of PML, including KLHL20, UHRF1, UBE3A and RNF4, which may drive the development of cancers at least partially through PML downregulation." (PMID 40002221, 2025). "KLHL9 has not been implicated in cancer, but highly homologous members of the KLHL family have such as KEAP1 and KLHL20 – both of which are notable tumour suppressors." (PMID 26781748, 2016).
tumor (8 papers, 2012 to 2025). "In the hypoxic tumor microenvironment, KLHL20 at elevated levels targets PML for constitutive degradation, reducing the number of PML-NBs and impairing tumor-suppressive functions." (PMID 40002221, 2025). "After the initial NACT, the downregulated mir-141 was associated with positive regulation of several suggested tumor suppressors, such as IRF6, BCL2, KLHL20." (PMID 35200555, 2022). "While KLHL20 mainly plays a tumor-promoting role, SPOP elicits both tumor-promoting and suppressive effects depending on its subcellular localization and cell context." (PMID 27200299, 2016). "Through degradation of PML, KLHL20 is expected to elicit oncogenic roles by blocking PML tumor-suppressive effects." (PMID 27200299, 2016). "Taken together, KLHL20 can not only amplify tumor hypoxia responses to stimulate angiogenesis in tumor microenvironments but also function directly in endothelial cells to promote their migration and sprouting angiogenesis." (PMID 27042198, 2016). "Thus, KLHL20-mediated PML ubiquitination results in not only the inhibition of PML tumor-suppressive functions but also a robust induction of various tumor hypoxia responses to contribute to the aggressiveness of diseases." (PMID 27200299, 2016). "Furthermore, KLHL20 is upregulated in certain tumors and possesses pleiotropic tumor-promoting functions through potentiating the degradation of tumor suppressor proteins DAPK and PML." (PMID 27042198, 2016). "Furthermore, KLHL20 is expected to elicit certain oncogenic roles through blocking the tumor suppressive effects of PML." (PMID 27042198, 2016). "Importantly, KLHL20 is demonstrated to act as a positive regulator of various tumor hypoxia responses through PML degradation." (PMID 27042198, 2016). "Indeed, KLHL20 confers tumor-promoting functions, such as transformation, migration, and survival, which are dependent on PML downregulation." (PMID 27042198, 2016). "Importantly, this hypoxia-induced, KLHL20-mediated PML ubiquitination pathway not only attenuates PML tumor suppressive functions but also participates in a feedback mechanism to maximize the production of HIF-1α during hypoxic stress." (PMID 22935031, 2012). "Death-associated protein kinase is not the only tumor-suppressor protein targeted by KLHL20." (PMID 27200299, 2016). "Consequently, KLHL20-PML pathway amplifies multiple tumor hypoxia responses, such as metabolic reprogramming, epithelial-mesenchymal transition, migration, tumor growth, angiogenesis, and chemoresistance, and these functions collectively lead to aggressive tumor phenotypes." (PMID 22935031, 2012). "Transcription of the KLHL20 gene is upregulated by the hypoxia-inducible factor HIF-1α, leading to its overexpression in hypoxic tumor cells." (PMID 31279627, 2019). "The important role of KLHL20 in hypoxia signaling is not confined to tumor cells." (PMID 27042198, 2016).
KLHL20 also shares sentences with these, for which no sentence is quoted: Bardet-Biedl syndrome 18 (1 paper); bipolar disorder (1); cervical carcinoma (1); Corneal opacity (1); Cyanosis (1); hepatitis C virus infection (1); neurodevelopmental disorder (1); prostate adenocarcinoma (1); psychiatric diseases (1); respiratory failure (1).